LCOR (ligand dependent nuclear receptor corepressor)
Description:
May act as transcription activator that binds DNA elements with the sequence 5'-CCCTATCGATCGATCTCTACCT-3' (By similarity). Repressor of ligand-dependent transcription activation by target nuclear receptors. Repressor of ligand-dependent transcription activation by ESR1, ESR2, NR3C1, PGR, RARA, RARB, RARG, RXRA and VDR.
Synonyms: C10orf12; KIAA1795; MLR2; FLJ38026; DKFZP564P1916; FLJ13022
Tractability: PROTAC: UniProt records ubiquitination sites on it.
Gene: Protein-coding gene on chromosome 10 (96,831,803 to 96,995,956, forward strand). Ensembl gene ENSG00000196233.
Subcellular location: Nucleus
Subcellular location (Human Protein Atlas): Nucleoplasm
Gene Ontology:
Molecular function: histone deacetylase binding; histone methyltransferase binding; nuclear estrogen receptor binding; protein binding; transcription corepressor activity; transcription corepressor binding; ubiquitin-specific protease binding; DNA binding
Biological process: cellular response to estradiol stimulus; negative regulation of transcription by RNA polymerase II; heterochromatin formation; regulation of transcription by RNA polymerase II
Cellular component: nucleoplasm; ESC/E(Z) complex; nucleus
Genetic constraint (gnomAD): Loss-of-function variants: 14 observed, 64.76 expected, observed/expected ratio (o/e) 0.22, 90% interval 0.14 to 0.34. The upper end of that interval is the gene's LOEUF score, 0.34, which puts it in group 1 of 6, group 1 being the genes least tolerant of losing a copy. Missense variants: 1,489 observed, 1,722.9 expected, observed/expected ratio (o/e) 0.86, 90% interval 0.83 to 0.9. Synonymous variants: 569 observed, 624.06 expected, observed/expected ratio (o/e) 0.91, 90% interval 0.85 to 0.98.
Homologues: Orthologues: chimpanzee LCOR (99% identical), macaque LCOR (96% identical), dog LCOR (82% identical), pig LCOR (80% identical), rabbit LCOR (77% identical), guinea pig LCOR (70% identical), rat Lcor (67% identical), mouse Lcor (66% identical). Paralogues in human: LCORL (16% identical).
Diseases named in the same sentence as LCOR in open-access papers:
LCOR is named in the same sentence as 19 diseases in open-access papers, as found by Europe PMC text mining. Sharing a sentence is not in itself a finding about the gene and the disease. The quoted sentences say what the papers report.
breast cancer (11 papers, 2017 to 2025). A primary or metastatic malignant neoplasm involving the breast. "LCOR activates transcription and can promote the development of breast cancer and the low differentiation of cervical intraepithelial neoplasia." (PMID 36685103, 2022). "The aim of this study was to investigate the expression of two nuclear receptor transcriptional coregulators, namely RIP140 (receptor-interacting protein of 140 kDa) and LCoR (ligand-dependent corepressor) in unifocal versus multifocal breast cancers." (PMID 30669416, 2019). "Like RIP140, overexpression of LCoR represses estrogen-dependent gene expression and decreased breast cancer cell proliferation." (PMID 29285256, 2017). "Furthermore, RIP140 is essential for repressive activity of LCoR in breast cancer cell proliferation." (PMID 32157438, 2020). "Jalaguier and colleagues (2017) could show that LCoR mRNA is expressed higher in breast cancer cell lines than in normal samples." (PMID 32157438, 2020). "In breast cancer cell lines, LCoR is regulated by RIP140 and inhibits cell proliferation." (PMID 32157438, 2020). "LCoR and RIP140 form a nuclear complex in breast cancer cells and are of prognostic value in further prostate and cervical cancer." (PMID 32157438, 2020). "LCoR overexpression and parallel downregulation of RIP140 mRNA leads to an increase in cell proliferation in breast cancer cell lines." (PMID 32157438, 2020). "Moreover, RIP140 and LCoR expression were strongly correlated in breast cancer cell lines and biopsies and correlated with overall survival of patients with breast cancer thus highlighting their strong interplay for the control of gene expression and cell proliferation in breast cancer cells." (PMID 29340045, 2017). "In breast cancers, RIP140 and LCoR mRNA expression were also found significantly higher in breast tumor samples as compared to normal mammary glands." (PMID 29340045, 2017). "In breast cancer cells, it was demonstrated that RIP140 was able to transactivate the LCOR gene promoter." (PMID 29340045, 2017). "LCOR had been identified as a tumor suppressor in prostate cancer and a recent study showed that the miR-199a-LCOR-IFN axis is a critical regulator maintaining the stem cell phenotype in breast cancer." (PMID 36033338, 2022).
breast tumor (2 papers, 2017 to 2022). "Interestingly, LCOR has been reported as a target of miR-199a in mammary stem cells and to influence initiation of ER-breast tumors." (PMID 36613642, 2022).
cervical cancer (2 papers, 2017 to 2020). A primary or metastatic malignant neoplasm involving the cervix. "The aim of the study was to analyze the expression of RIP140 and its partner LCoR in cervical cancers, to decipher their relationship with histone protein modifications and to identify a potential link with patient survival." (PMID 29285256, 2017). "In a previous study we could show that patients with cervical cancer expressing low levels of LCoR and RIP140 correlate with a better overall survival than patients expressing high levels of RIP140." (PMID 32157438, 2020). "In conclusion, RIP140 and LCoR transcription factors may lead to the progression of cervical cancer, and possibly represent novel therapeutic targets for the treatment of this malignancy." (PMID 29285256, 2017). "Modulation of RIP140 and LCoR may represent a novel targeting strategy for cervical cancer prevention and therapy." (PMID 29285256, 2017). "Additionally, the mechanisms of how RIP140 and LCoR interact with other pathways in order to influence the development of cervical cancer have to be studied." (PMID 29285256, 2017). "In addition, because there is a direct correlation between RIP140 and LCoR with the histone protein modifications H3K4me3 and H3K9ac, analysis of their involvement in the maintenance of the epigenome should be investigated in cervical cancer." (PMID 29285256, 2017). "Since neither RIP140 nor LCoR has been studied in cervical cancer, this investigation represents the first analysis of these transcription factors in this pathology." (PMID 29285256, 2017). "RIP140 is no longer a significant negative prognosticator for cervical cancer when LCoR expression is low." (PMID 29285256, 2017).
cervical intraepithelial neoplasia (2 papers, 2020 to 2022). "Aim of this study was to analyze the expression of LCoR and RIP140 in cervical intraepithelial neoplasia grade I, II and III (CIN I–III) and the correlation of their expression regarding the progression of cervical dysplasia." (PMID 32157438, 2020).
colon carcinoma (2 papers, 2017 to 2018). "In the present study, we further decipher by IHC, the expression of RIP140 in colon carcinomas and analyzed, for the first time, the expression of the LCOR gene (recently identified as a RIP140 interactor and target gene) in this malignancy." (PMID 29340045, 2017). "In HT29 colon cancer cells, mRNA expression of PLOD2, HADH and LCOR as well as AXIN2 as a canonical control target was downregulated upon treatment with the Porcupine inhibitor LGK974." (PMID 29453334, 2018). "Taken together, these experiments confirmed PLOD2, HADH, and LCOR as non-canonical Wnt targets that depend on Wnt secretion but not on β-catenin in colon cancer cell lines as well as primary colon cancer cells and MEFs." (PMID 29453334, 2018). "Independent experiments confirmed several target genes, including PLOD2, HADH, LCOR and REEP1 as non-canonical target genes in various colon cancer cells." (PMID 29453334, 2018). "Silencing of ATF2 revealed downregulation of PLOD2, HADH, LCOR and REEP1 mRNA expression; thus suggesting ATF2 as the transcription factor in non-canonical Wnt signaling in colon cancer cells." (PMID 29453334, 2018).
gastric cancer (2 papers, 2017 to 2025). A primary or metastatic malignant neoplasm involving the stomach. "Our data first demonstrate a significant positive association between RIP140 and LCOR gene expression both in colon and gastric cancers." (PMID 29340045, 2017). "In gastric cancer, high LCoR expression was identified as an independent marker of poor prognosis suggesting a key role in this malignancy." (PMID 29340045, 2017).
prostate carcinoma (2 papers, 2020 to 2022). A carcinoma that arises from epithelial cells of the prostate gland. "LCoR is described as a tumor suppressor in prostate cancer and an inhibitor of cell growth in prostatic cancer cells." (PMID 32157438, 2020). "Asim and colleagues could show that LCoR inhibits prostate cancer growth in a xenograft mouse model via co-repression of activated androgen receptor (AR)." (PMID 32157438, 2020).
B-cell lymphoma (1 paper, 2017). "LCOR, a component of a histone deacetylation complex, is mutated in B-cell lymphoma, suggesting a role in B-lymphopoiesis, but this factor has not previously been implicated in HSC function and its role remains to be defined." (PMID 28514439, 2017).
chordoma (1 paper, 2022). Chordomas are rare malignant tumors arising from embryonic remnants of the notochord in axial skeleton. "Significantly lower expression of LCOR (ligand-dependent nuclear receptor corepressor) gene in chordoma can be caused in part by the upregulation of seven miRNAs (miR-101, miR-142, miR-144, miR-148, miR-182, miR-199a, and miR-424), which are predicted or validated regulators of the LCOR mRNA." (PMID 36033338, 2022). "Functional annotation of the mRNA targets predicted a miRNA-mRNA network regulating the self-renewal potential of chordoma tumors, through the regulation of the transcription factor LCOR, and the potential activation of the Hippo pathway through targeting its regulators, TAOK and MOB1." (PMID 36033338, 2022). "This might be especially important in understanding the complex miRNA-dependent regulation of LCOR if novel therapeutical approaches are considered to target the LCOR-mediated IFN-responsiveness in chordoma." (PMID 36033338, 2022). "Other regulators of stemness, such as MYBL1 and RECK are also predicted targets for multiple upregulated miRNAs in our study, and, together with LCOR and YAP/TAZ may form a regulatory network maintaining the stem-cell phenotype in chordoma." (PMID 36033338, 2022).
colorectal tumors (1 paper, 2017). "The IHC staining for both RIP140 and LCoR decreased in colorectal tumors as compared to adjacent normal tissue which is, for RIP140, in agreement with a previous study." (PMID 29340045, 2017).
triple-negative breast carcinoma (1 paper, 2023). An invasive breast carcinoma which is negative for expression of estrogen receptor (ER), progesterone receptor (PR), and human epidermal growth factor receptor 2 (HER2). "LCOR has been identified as a potential target to improve the efficiency of immune checkpoint blockade in triple-negative breast cancer." (PMID 38020758, 2023).
tumor (13 papers, 2017 to 2026). "This recruitment of LCoR to androgen-bound AR inhibits AR action associated with inhibition of tumor progression in xenograft tumors of CRPC cells." (PMID 33810413, 2021). "RIP140 and LCoR expression was then correlated with clinical parameters linked to tumor aggressiveness and prognosis." (PMID 30669416, 2019). "Interestingly, MYSM1-associated gene LCOR has been established to act as a corepressor of nuclear hormone receptors and inhibit tumor growth and hepatic lipogenesis via physically interacting with liganded receptors." (PMID 31761786, 2019). "By manipulating ERα interaction with LCOR, we tested the effects of LCOR-mediated APM induction on HR+ tumor immunity." (PMID 41289011, 2026). "This nuclear receptor–independent function of LCOR increases tumor immunogenicity and visibility to the immune system, which has been shown to be beneficial for immunotherapy in preclinical models, leading to complete eradication of TNBC tumors." (PMID 41289011, 2026). "Mechanistically, we found that ERα hijacked LCOR, a nuclear receptor corepressor, thereby preventing LCOR’s function in the induction of tumor immunogenicity and immune infiltration, which is normally observed in the absence of ERα, such as in ER– BC." (PMID 41289011, 2026). "LCOR acts as a co-suppressor, binding various essential nuclear receptors in cancers, activating downstream signals and influencing the tumor progression." (PMID 40083699, 2025). "H&E staining and live small animal imaging on basis of nude mice tail vein injection showed that LCOR overexpression obviously reduced the metastatic nodes number in the liver and repressed tumor metastasis." (PMID 40083699, 2025). "The introduction of LCOR mRNA into tumor cells can restore the expression of LCOR, a tumor suppressor, by modulating IFN sensitivity." (PMID 37416764, 2023). "Others such as LCoR (ligand dependent corepressor), inhibit AR-mediated transcription by interacting with HDACs and CtBP (C-terminal binding protein), which suppress tumor growth in vivo." (PMID 35269520, 2022). "Overall, these human preclinical assays demonstrate that disruption of LCOR and ERα interactions reconfigured HR+ tumor immunity toward high immune reactivity and posit the molecular targeting of ERα-LCOR interactions as a potential immune-based therapy in HR+ BC tumors." (PMID 41289011, 2026). "Given LCOR exerts a pivotal efficacy in tumor progression and lipid metabolism, whereas its expression profile and functional significance in ccRCC remain unexplored, it necessitates to illustrate the role of LCOR in ccRCC." (PMID 40083699, 2025). "Thus, it suggests that the activation of the membrane-associated Src non receptor tyrosine kinase negatively regulates LCoR co-repressor activity and thereby promotes tumor development." (PMID 33810413, 2021). "Finally, a positive and significant correlation between RIP140 and LCoR expression was observed in the two tumor types (p < 0.01) confirming our previous observation." (PMID 30669416, 2019). "The difference in the correlation with survival of RIP140 and LCoR in CRC compared to GC may reflect the different contribution of the two transcriptional coregulators to tumor development and progression in these epithelia." (PMID 29340045, 2017). "IHC results of subcutaneous tumors also unveiled that the expression of LCOR, PLCL1 and UCP1 increased and the tumor malignant index Ki67 decreased after LCOR overexpression." (PMID 40083699, 2025). "RBPMC2 and DSC3 were found as independent prognostic biomarkers of tumor progression and CALD1 and LCOR were identified as prognostic biomarkers of CSS between both groups." (PMID 33731721, 2021). "Progressive and de novo MIBC groups present different prognostic biomarkers for tumor progression (RBPMS2 in progressive MIBC and DSC3 in de novo MIBC) and for CSS (CALD1 in progressive MIBC and LCOR in de novo MIBC)." (PMID 33731721, 2021).
tumor (continued). "In both tumor types, RIP140 and LCoR expression was correlated with each other and with expression of ERβ." (PMID 30669416, 2019). "Both LCOR and SMG1 protein are known to function as a tumor suppressor in multiple cancers and mediate the repression of tumor growth by regulating oncogenic proteins involved in cell cycle." (PMID 31761786, 2019). "RIP140 and LCoR expression were correlated with various clinicopathological parameters in CRC and/or GC including TNM stage and tumor differentiation." (PMID 29340045, 2017). "We found that Bcl-2, an inhibitor of apoptosis, was downregulated in LCOR overexpressed cell lines, indicating that p38 exerted pro-apoptotic function rather than pro-tumor efficacy." (PMID 40083699, 2025). "Interestingly, expression of LCOR, a corepressor that is recruited to LXR upon agonist binding, was even more drastically reduced in primary ER-negative tumours (two-tailed Mann–Whitney U test: p < 0.0001,)." (PMID 31683867, 2019). "RIP140 and LCoR expression correlated with TNM and tumor differentiation." (PMID 29340045, 2017). "Mechanistically, RUNX1 was a transcriptional suppressor of PLCL1, LCOR could interact with RUNX1 to relieve RUNX1-mediated repression of PLCL1, leading to increased PLCL1 expression, which, in turn, inhibited the tumor progression and lipid accumulation in ccRCC." (PMID 40083699, 2025). "Our study unveiled a potential molecular mechanism for the development of ccRCC, demonstrating that LCOR could interact with RUNX1 to relieve RUNX1-repressed PLCL1 transcription, leading to the upregulation of PLCL1 expression, which inhibited the tumor progression and lipid accumulation in ccRCC." (PMID 40083699, 2025). "CCT5, LCOR, and ZNF367 were evidently overexpressed in tumor tissues compared with adjacent tissues (all P < 0.001), while FOS was significantly downregulated in tumor tissues compared with non-tumor tissues of HCC patients (P < 0.001)." (PMID 34522182, 2021).
cancer (7 papers, 2017 to 2023). A tumor composed of atypical neoplastic, often pleomorphic cells that invade other tissues. "Ligand-dependent corepressor (LCOR) is a protein regulating cell differentiation in normal or cancer cells." (PMID 35912168, 2022). "It thus appears that RIP140 and LCOR gene expression is strongly correlated in different cancer types." (PMID 29340045, 2017). "Several studies have reported data concerning the regulation of RIP140 expression and post-translational modifications whereas little is known concerning LCOR gene regulation in cancer cells and tissues." (PMID 29340045, 2017). "Taken together, the studies suggest important roles of LCoR in regulating hormone-induced pathways and the development of cancer." (PMID 28125049, 2017). "The transcription coregulators RIP140 and LCoR are part of a same complex which controls the activity of various transcription factors and cancer cell proliferation." (PMID 29340045, 2017). "The restored LCOR expression led to increased immunoproteasome activity, elevated MHC expression and many other APM‐related benefits and consequently revived the cancer cell antigen presentation." (PMID 37403792, 2023). "Among these, LCOR and PDE7A have been shown to play roles in other types of cancer." (PMID 36685103, 2022). "Ligand-dependent corepressor (LCoR) and receptor-interacting protein 140 (RIP140/NRIP1) play an important role in the regulation of multiple oncogenic signaling pathways and the development of cancer." (PMID 32157438, 2020).
infection (1 paper, 2019). The state of being infected such as from the introduction of a foreign agent such as serum, vaccine, antigenic substance or organism. "There was no change in LCOR mRNA levels at each infection time point." (PMID 31784561, 2019).
LCOR also shares sentences with these, for which no sentence is quoted: B-cell acute lymphoblastic leukemia (1 paper); lung adenocarcinoma (1); lymph node metastasis (1); myeloma (1); ovarian carcinoma (1).